WNT9A (Wnt family member 9A)
Diseases named in the same sentence as WNT9A in open-access papers (continued):
Sharing a sentence is not in itself a finding about the gene and the disease.
uveitis (1 paper, 2018). An inflammatory process affecting a part of or the entire uvea. "Similarly, WNT2B (ENSP00000358698), WNT9A (ENSP00000272164), WNT4 (ENSP00000290167), and WNT2 (ENSP00000265441) all participate in the pathogenesis of uveitis through the regulation of urea cells, thus validating their strong relationships with uveitis." (PMID 30349554, 2018).
cancer (21 papers, 2011 to 2025). A tumor composed of atypical neoplastic, often pleomorphic cells that invade other tissues. "Hypermethylation of Wnt signaling in general has been implicated in a variety of cancers, including hypermethylation of WNT9A and FZD9 genes." (PMID 40188944, 2025). "Recent temporal profiling of stromal fibroblast populations in the healthy and cancerous mouse mammary gland uncovers Wnt9a as a senescence inducer in cancer-associated myofibroblasts." (PMID 40312497, 2025). "By analyzing the expression and prognosis of WNT family genes in pan-cancer, we found that WNT9A was overexpressed in most tumors and indicated poor prognosis." (PMID 34565373, 2021). "“Pathways in cancer” included genes such as Wnt9a, Shh, and zinc finger transcription factors, suggesting involvement in cell cycle." (PMID 26229004, 2015). "Analysis of RNA-seq and miRNA-seq data from several NSCLC patients suggested that alterations in WNT9A might impact cancer progression by affecting the interference between lncRNAs, miRNAs, and mRNAs." (PMID 35957916, 2022). "In addition to the already-known targets, we further identified relevant cancer-associated genes; such as, FGFR1, VEGFA, WNT9A, and FZD4." (PMID 35132075, 2022). "Cancer metastasis signaling was linked with JAK kinase, Wnt family member 9A (WNT9A), IL6, and prostaglandin-endoperoxide synthase 2 (PTGS2); whereas interleukin 1 receptor associated kinase 4 (IRAK4), and histone h3 were associated with p38MAKP signaling pathway." (PMID 30972102, 2019). "We then analysed the expression of WNT ligands (WNT7B, WNT9A, WNT3A, WNT4) in RBL2-LOH cancer cell lines (HCC1500 and Cal-51) and in RBL2-wildtype cancers (MCF7 and T47D)." (PMID 38678032, 2024). "On the other hand, the upregulated genes, such as GNG12, GNG4, WNT9A, EDNRB, FGF18, LAMA3, MMP2, etc., were found in pathways in cancer." (PMID 36239109, 2022). "Conversely, the cancer cell–derived WNT7A, WNT7B, and WNT10A and stromal WNT3 and WNT9A were highly expressed in the squamous subtype." (PMID 35536676, 2022). "These genes included well-known cancer-promoting factors, such as EGFR, WNT9A, and MAP2K2." (PMID 34272396, 2021). "Genes related to cancer pathways were downregulated upon atezolizumab treatment, including angiogenic factors for tumor vascularization (TNK1, AREG and KDR), proto-oncogenes (RET and MET) and tumor cell survival/migration/invasion (CDH1, RARA, WNK2, WNT4A, WNT9A, TGFB2, EGF, and LAMA3)." (PMID 32616706, 2020).
tumor (21 papers, 2011 to 2025). "A PANTHER analysis of identified gene sets uncovered that Wnt9a expression was enriched in tumor-associated senCAFs." (PMID 40312497, 2025). "WNT9A has tumor suppressor features in that it drives the differentiation of chondrocytes and can inhibit cell proliferation." (PMID 40188944, 2025). "Second, the overexpression of FRA1 downregulated the expression of the following genes involved in transformation and tumor promotion: WNT9A, AXIN2, and MYB." (PMID 37830558, 2023). "Screening for Wnt ligand expression by qPCR revealed that Wnt7b, Wnt9a and to a lesser extent Wnt3a, were significantly elevated in H2-c-fosLTR tumor-bearing bones and tumors." (PMID 32686768, 2020). "A cohort of 98 OS patients analyzed by RNA-seq was analyzed for WNT7B and WNT9A expression in the tumor and four groups were generated according to the expression of the two genes around their respective means." (PMID 32686768, 2020). "Other ligands of the network include WNT2B, WNT5A, and WNT9A, differentially expressed by tumor cells and TAMs." (PMID 27215396, 2016). "Nevertheless, while all these maneuvers produced results that were quantitatively significant and qualitatively consistent with a role for Wnt9A as a tumor suppressor, the magnitude of proliferation inhibition observed cannot be attributed to the effects of Wnt9A alone." (PMID 27049382, 2016). "The results presented herein suggest that the non-canonical Wnt ligand, Wnt9A has the potential to act as a tumor suppressor in cells that have sustained oncogenic mutations sufficient to hyperactivate β-catenin action." (PMID 27049382, 2016). "Combined expression of WNT ligands (WNT3A, WNT4, WNT7B, WNT9A, WNT10A, WNT11) in BRCA patient tumours has a positive correlation (R = 0.27, p value = 0) with the combined expression of key EMT-inducing transcription factors SNAI1, SNAI2, ZEB1, ZEB2 and TWIST1." (PMID 38678032, 2024). "Finally, the levels of genes involved in the tumor EMT, such as CDH2, CDH11, SMAD2, SMAD3, WNT9A, and SP-1, were significantly downregulated after the SH intervention." (PMID 41444284, 2025). "Concerning the radiobiological effects, it has been found that I-125 could inhibit cell proliferation in vitro and delay tumor growth in tumor models by upregulating apoptosis- and cell arrest-related genes, such as BNIP3 and WNT9A, through irradiation-induced DNA methylation." (PMID 34660280, 2021).
metabolic disease (2 papers, 2022 to 2025). A congenital disorder (due to inherited enzyme abnormality) or acquired (due to failure of a metabolically important organ) disorder resulting from an abnormal metabolic process. "Interestingly, WNT9A and WISP2 are part of the Wnt‐signaling pathway, which is known to be involved in aging‐related biological processes and metabolic disorders (Gruber, Yee, and Tolwinski 2016)." (PMID 39812213, 2025).
WNT9A also shares sentences with these, for which no sentence is quoted: basal cell carcinoma (2 papers); leukaemia (2); rheumatoid arthritis (2); Alzheimer disease (1); bladder cancer (1); breast adenocarcinoma (1); chondrosarcoma (1); chronic myeloid leukaemia (1); cognitive decline (1); cognitive deficits (1); colorectal (1); colorectal adenocarcinoma (1); endometrial cancer (1); glioblastoma multiforme (1); glioma (1); hand osteoarthritis (1); Hypergonadotropic hypogonadism (1); hypertrophic cardiomyopathy (1); infection (1); membranous nephropathy (1); non-small cell lung carcinoma (1); Obesity (1); Primary amenorrhea (1); pulmonary fibrosis (1); sarcoma (1); ulcerative colitis (1).